STIP1 (stress induced phosphoprotein 1)
Diseases named in the same sentence as STIP1 in open-access papers (continued):
Sharing a sentence is not in itself a finding about the gene and the disease.
Stroke (6 papers, 2013 to 2022). Sudden impairment of blood flow to a part of the brain due to occlusion or rupture of an artery to the brain. "STIP1 is a co-chaperone with reported neuroprotective capacities in mouse Alzheimer’s disease and stroke models." (PMID 35626686, 2022). "This is important, given that increased STIP1 levels might be protective against insults such as stroke-mediated cell death and in Alzheimer's disease." (PMID 26398952, 2015).
Alzheimer disease (5 papers, 2015 to 2022). A progressive, neurodegenerative disease characterized by loss of function and death of nerve cells in several areas of the brain leading to loss of cognitive function such as memory and language. "Elevated secretion of STIP1 by astrocytes was observed under ischemic insult as well as in the brains of Alzheimer’s disease patients." (PMID 35626686, 2022). "In Alzheimer’s disease models, STIP1 inhibited β-amyloid binding to PrPC, attenuating β-amyloid-induced neurotoxicity in mouse primary hippocampal neurons." (PMID 35626686, 2022). "Moreover, STIP1 also modulates toxicity of Aβ peptides in models of Alzheimer's disease." (PMID 26398952, 2015).
autism (5 papers, 2016 to 2025). Persistent deficits in social interaction and communication and interaction as well as a markedly restricted repertoire of activity and interest as well as repetitive patterns of behavior. "The authors used the immuno-dominant B-cell epitopes of LDH-A, LDH-B, STIP1 and CRMP1 to produce an antigen-driven model based on the autism-specific 37/73 kDa band pattern." (PMID 32784803, 2020). "Early clinical studies identified that mothers with the combination of LDHA/B+STIP1+CRMP1 autoantibodies had children with a more severe autism phenotype compared to mothers of children with autism who lacked autoantibodies." (PMID 39929953, 2025). "It has been shown that autoantibodies targeting the intracellular proteins LDH-A and LDH-B, STIP1 and CRMP1 are able to induce autism-related behavioral changes in a mouse model, however, but how these antibodies target their antigens is also still unknown." (PMID 36816132, 2023).
colorectal cancer (4 papers, 2017 to 2025). A primary or metastatic malignant neoplasm that affects the colon or rectum. "For instance, high STIP1 expression correlates with poor overall survival in colorectal cancer patients, while STIP1 knockdown inhibits colorectal cancer cell proliferation, migration, and invasion." (PMID 41163796, 2025).
glaucoma (4 papers, 2009 to 2024). Increased pressure in the eyeball due to obstruction of the outflow of aqueous humor. "We previously discovered that variants in yeast U3 protein 21 (UTP21), homologous to those found in WDR36 in glaucoma patients, alter cell proliferation in strains deficient for the co-chaperone protein stress-induced-phosphoprotein 1 (Sti1p)." (PMID 21850170, 2011). "We examined the heat shock protein 70/90 (HSP70/90)-organizing co-chaperone stress-induced-phosphoprotein 1 (STI1) as a potential co-modifying gene in glaucoma patients found to harbor WDR36 amino acid variation." (PMID 21850170, 2011). "In yeast models, certain Utp21 variants homologous to glaucoma-associated variants in human WDR36 cause functional defects in a stress-induced-phosphoprotein 1 (Sti1) mutant background, arguing that WDR36 contributes to polygenic forms of glaucoma." (PMID 19347049, 2009).
Hypoglycemia (4 papers, 2021 to 2023). A decreased concentration of glucose in the blood. "In the post-hypoglycemia follow-up period, most proteins normalized to baseline by 24-h; however, STIP1 (p = 0.003), UBE2N (p = 0.004) and UBE2L3 (p < 0.04) were decreased in controls at 24-h." (PMID 34426634, 2021). "UBE2N and STIP1 were higher from 0.5-h to 2 h post-hypoglycemia in T2D compared to control." (PMID 34426634, 2021). "At hypoglycemia, UBE2N, STIP1, and UBE2L3 increased in T2D compared to baseline (p < 0.05, p < 0.05, and p < 0.05, respectively), a change not seen in controls." (PMID 34831332, 2021). "In accord with the findings in severe hypoglycemia, there were significant increases in UBE2N, STIP1, and UBE2L3 seen in hypoglycemia only in the T2D cohort that returned to baseline by 24 h." (PMID 34831332, 2021). "At hypoglycemia, UBE2N, STIP1, and UBE2L3 increased (all p < 0.05), whilst TLR4:MD-2 and HSPA8 decreased (p < 0.05) in T2D versus baseline." (PMID 34831332, 2021). "STIP1 (RFU): 4512.7 ± 208.3 vs 3698.0 ± 129.5, 0.5-h post-hypoglycemia, p < 0.01; 4709.9 ± 384.8 vs 3858.5 ± 182.1, 1 h post-hypoglycemia, p < 0.05; 4618.0 ± 277.2 vs 3745.7 ± 255.6, 2 h post-hypoglycemia, p < 0.05." (PMID 34426634, 2021). "In the time course following hypoglycemia, UBE2N, UBE2L3 and STIP1 were significantly and persistently higher in T2D compared to normal controls for up to 24-h, suggesting that in T2D the heat shock and related proteins are preconditioned for an enhanced response." (PMID 34426634, 2021). "Why the levels of UBE2N, UBE2L3 and STIP1 should fall in the control subjects in response to hypoglycemia, whilst UBE2G2 showed no apparent change in level, is unclear, and whether the loss of regulation of these specific and tightly controlled proteins would lead to a detrimental effect is unknown." (PMID 34426634, 2021). "Notably UBE2N, UBE2L3, and STIP1 all significantly go down in controls but not at all in T2D in response to hypoglycemia, whilst the protein that is linked within the system, UBE2G2, was unaffected by hypoglycemia, though significantly lower than levels seen in T2D at all time points." (PMID 34426634, 2021).
endometriosis (3 papers, 2018 to 2024). The growth of functional endometrial tissue in anatomic sites outside the uterine body. "In summary, our data suggest a potential role of STIP1 in endometriosis susceptibility, which may occur through the modulation of MMP-9 functions in a fashion independent of several known signaling proteins, such as NF-kB, ERK, AKT, and JAK2." (PMID 29304094, 2018). "In brief, our data suggest an association between STIP1 levels and endometriosis/adenomyosis." (PMID 29304094, 2018). "Both epithelial and stromal cells of endometriotic lesions showed expression of STIP1, and serum levels of STIP1 were higher in endometriosis patients compared to controls." (PMID 36612107, 2022). "Serum CA125 levels were superior to STIP1 levels in the detection of endometriosis (specificity, 95.0%; sensitivity, 75.7%)." (PMID 29304094, 2018). "Both epithelial and stromal cells in surgical tissues of endometriosis and adenomyosis expressed STIP1 and MMP-9." (PMID 29304094, 2018). "Serum STIP1 levels were measured in 222 patients with pathologically-proven endometriosis and/or adenomyosis (mean age, 40.1 ± 7.7 years) and 222 age-matched control women (mean age, 40.1 ± 7.7 years)." (PMID 29304094, 2018). "STIP1 is thought to regulate the expression of MMPs; moreover, endometriosis shares certain features with cancers in which STIP1 has been shown to play a role." (PMID 29304094, 2018). "The main strength of our study is its comprehensive examination of the role of STIP1 in endometriosis through multiple experimental perspectives (i.e., assessment of its circulating levels, immunohistochemistry, and functional assays)." (PMID 29304094, 2018). "This case-control study investigates STIP1 serum levels and tissue expression in relation to endometriosis/adenomyosis in Taiwanese population." (PMID 29304094, 2018). "Specifically, we designed the current case–control study to investigate serum STIP1 levels and tissue expression in relation to endometriosis in a Taiwanese population." (PMID 29304094, 2018). "A cutoff value of 98.6 ng/mL for serum STIP1 levels had a 95% specificity for the diagnosis of endometriosis, although the sensitivity dropped to 18.9%." (PMID 29304094, 2018). "The preoperative serum STIP1 levels of patients with endometriosis/adenomyosis were significantly higher than those of the controls." (PMID 29304094, 2018). "Receiver operating characteristic (ROC) curve analysis revealed that the cutoff point that maximized both the sensitivity and specificity of serum STIP1 levels in the detection of endometriosis was 51.2 ng/mL (specificity, 79.3%; sensitivity, 53.6%)." (PMID 29304094, 2018). "In serial sections obtained from the same tissues, both epithelial and stromal cells of endometriosis/adenomyosis expressed STIP1 and MMP9." (PMID 29304094, 2018). "Second, the usefulness of serum STIP1 levels for the diagnosis of endometriosis seems limited." (PMID 29304094, 2018). "Our findings are in line with a previous report where STIP1 was shown to stimulate the activity of MMPs; moreover, several studies have indicated that MMP-9 is upregulated in endometriosis." (PMID 29304094, 2018). "The presence of both serum STIP1 > 51.2 ng/mL and CA125 > 35 U/mL had 100% specificity for endometriosis, but sensitivity was as low as 39.2%." (PMID 29304094, 2018). "Furthermore, stress-induced phosphoprotein-1 (STIP-1), an adaptor protein for Hsp70 that is up-regulated in the circulation of patients with endometriosis, is known to regulate cell migration via matrix metalloproteinase 9 (MMP-9) and metastasis." (PMID 39519195, 2024). "Sensitivity, specificity, positive and negative predictive values, and accuracy of serum STIP1 and CA125 levels in the detection of endometriosis." (PMID 29304094, 2018).
esophageal squamous cell carcinoma (3 papers, 2017 to 2025). Esophageal squamous cell carcinoma (ESCC) is a type of esophageal carcinoma (EC) that can affect any part of the esophagus, but is usually located in the upper or middle third. "High STIP1 expression was associated with shorter overall survival in patients with papillary thyroid carcinoma, and STIP1 serological autoantibodies were correlated with early-stage esophageal squamous cell carcinomas." (PMID 36713524, 2022). "Moreover, our study delineates a novel pathway in esophageal squamous cell carcinoma whereby STIP1 enhances the interaction between AHCY and LDHA, enabling AHCY to recruit PRMT3 to methylate LDHA at R106." (PMID 41163796, 2025). "Our study elucidates a previously unrecognized oncogenic signaling axis in esophageal squamous cell carcinoma whereby the co‐chaperone STIP1 and metabolic enzyme AHCY are co‐opted to drive upregulation of the Warburg effect and promote ESCC progression." (PMID 41163796, 2025).
serous ovarian cancers (3 papers, 2013 to 2022). "Kaplan-Meier analyses also revealed that STIP1 histoscores >169 were significantly associated with poor OS both in all invasive cases of this study (n = 280) and in invasive serous ovarian cancers (n = 170)." (PMID 23468915, 2013). "Cell lysates from human serous ovarian cancer were subjected to western blot to measure endogenous JAK2 and STIP1 protein expression." (PMID 35269562, 2022). "Significantly positive correlations between STIP1 and JAK2 expression in serous ovarian cancers were identified (P < 0.05)." (PMID 27409672, 2016). "Finally, expression of STIP1 and JAK2 were positively correlated to each other in human serous ovarian cancer specimens." (PMID 35269562, 2022).
amyloidosis (2 papers, 2020 to 2025). A disorder characterized by the localized or diffuse accumulation of amyloid protein in various anatomic sites. "Interestingly, Stip1/Hop is found in amyloid beta aggregates in mice and humans, and increased levels of Stip1 seem to accelerate amyloidosis in AD mouse models." (PMID 39739753, 2025).
bladder cancer (2 papers, 2022 to 2023). "In advanced bladder carcinoma, high STIP1 expression significantly correlated with worse overall survival and chemotherapeutic pretreatment with a cisplatin-based regimen." (PMID 36839749, 2023). "Although we were unable to connect STIP1 overexpression and response to cisplatin, it was previously reported that STIP1 can be a predictor of cisplatin-resistance in bladder cancer patients, which are candidates to immunotherapy." (PMID 36713524, 2022).
depression (2 papers, 2015 to 2025). "In order to test for other neuropsychiatric-like behaviors as a result of altered STIP1 levels we tested both STITGA and STI1−/+ mice for anxiety-like behavior and depression-like behavior." (PMID 26398952, 2015). "Additionally, PTPN6, STIP1, ANPEP, and TSPYL1 were found to be correlated with major depressive disorder." (PMID 40520536, 2025). "Spatial learning and memory, as well as anxiety and depression-like behavior do not seem to be affected by reduced STIP1 levels." (PMID 26398952, 2015).
endometrial cancer (2 papers, 2016 to 2018). Primary or metastatic malignant neoplasm involving the endometrium (mucous membrane that lines the endometrial cavity). "The immunohistochemical expression of STIP1 and LSD1 showed positive associations in both ovarian (r = 0.59, p < 0.001) and endometrial cancer (r = 0.59, p < 0.0001) tissues." (PMID 29593255, 2018). "A STIP1 highly expressing endometrial cancer tissues exhibited higher levels of LSD1, whereas a STIP1 lowly expressing one had lower levels of LSD1." (PMID 29593255, 2018). "We therefore used RNA interference to examine the role of STIP1 in the regulation of the JAK-STAT pathway in ovarian and endometrial cancer cell lines." (PMID 27409672, 2016). "Here, we show that STIP1 stabilizes JAK2 protein in ovarian and endometrial cancer cells." (PMID 27409672, 2016).
esophageal cancer (2 papers, 2017 to 2025). A primary or metastatic malignant neoplasm involving the esophagus. "STIP1 also highly expression in esophageal cancer cells and tissues and is associating with poor prognosis." (PMID 41163796, 2025). "Though what mechanism might underlie the production of autoantibodies against STIP1 in esophageal cancer is unclear, our findings provide important clues for further study of biological function of STIP1 in ESCC." (PMID 28852266, 2017). "To investigate the mechanism of STIP1 in esophageal cancer progression, we performed pull‐down coupled with mass spectrometry (MS) analysis." (PMID 41163796, 2025). "In future work, we would perform a systematic study, including in vitro cell-based research and animal experiments, to reveal the function and molecular mechanisms of STIP1 in esophageal cancer." (PMID 28852266, 2017). "To date, there is not yet relevant research of STIP1 in esophageal cancer." (PMID 28852266, 2017). "However, no study has been conducted on STIP1 autoantibodies in esophageal cancer." (PMID 28852266, 2017).
ischaemic stroke (2 papers, 2013 to 2021). "In addition, elevated STIP1 expression was detected in cerebral specimens of humans and rats with ischaemic stroke, and STIP1 overexpression promoted recruitment of bone marrow–derived cells to ischaemic brain, and facilitated neurological recovery." (PMID 34734476, 2021).
ischemia (2 papers, 2013 to 2023). A hypoperfusion of the BLOOD through an organ or tissue caused by a PATHOLOGIC CONSTRICTION or obstruction of its BLOOD VESSELS, or an absence of BLOOD CIRCULATION. "Another study indicated that STIP1 treatment prevented ischemia‐mediated cell apoptosis, indicating the protective role of STIP1 against ischemia‐induced injury." (PMID 37904692, 2023).
lung carcinoma (2 papers, 2022). "Interestingly, there have been reports showing that STIP1 can support the growth and spread of lung cancer and melanoma through the JAK2/STAT3 pathway, a finding in accordance with our current preclinical data." (PMID 35269562, 2022).
lymph node metastasis (2 papers, 2018 to 2022). "A recent meta-analysis suggests that high STIP1 expression is significantly associated with shorter overall survival, early lymph node metastasis and more advanced clinical stage compared with low STIP1 expression in six studied cancer types." (PMID 36713524, 2022). "Previous studies have showed that STIP1 was associated with disease progression and poor prognosis in various types of cancers, particularly for those with advanced lymph node metastasis." (PMID 29335007, 2018).
Parkinson’s (2 papers, 2022 to 2024). "Moreover, in plasma samples from Parkinson’s disease subjects, STIP1-specific autoantibodies were found, suggesting an autoimmune component of the pathology." (PMID 39456899, 2024).
adenocarcinoma of the lung (1 paper, 2017). "The STIP1 gene was previously found rearranged with AHNAK in adenocarcinoma of the lung; however, in that particular case STIP1 constituted the 3′ moiety of the fusion whereas in the present case it is 5′." (PMID 28186972, 2017).
adenomyosis (1 paper, 2018). The growth of endometrial tissue inside the muscular wall of the uterine corpus. "Immunostaining for STIP1 was markedly positive in both ovarian endometriosis and adenomyosis." (PMID 29304094, 2018).
asthma (1 paper, 2020). "STIP1 rs2236647 was associated with asthma risk of children and GLCCI1 rs37969 mutant genotypes were associated with less improvement in airway hyper-responsiveness." (PMID 33208131, 2020). "Children with STIP1 rs2236647 CC genotype showed increased risk of asthma compared with the other two genotypes (p = 0.005)." (PMID 33208131, 2020). "An Arab study has indicated that the STIP1 rs2236647 C allele can be used as an asthma marker for adult." (PMID 33208131, 2020). "Our finding demonstrated that CC homozygotes of STIP1 rs2236647 polymorphism might be an asthma susceptibility marker in Chinese childhood asthma." (PMID 33208131, 2020). "Moreover, a white adult asthma study identified that STIP1 rs2236647 was associated with change in lung function after ICS treatment for 4 weeks." (PMID 33208131, 2020). "The aim of our study is to investigate the effects of STIP1 and GLCCI1 polymorphisms on the risk of childhood asthma and ICS response in Chinese asthmatic children." (PMID 33208131, 2020). "In conclusion, we found significant associations between the STIP1 rs2236647 polymorphism and the risk of childhood asthma, and GLCCI1 SNPs are related to the improvement of lung function in Chinese Han childhood asthma patients who received ICS for 3 months." (PMID 33208131, 2020). "It is worth mentioning that we are the first to report the function of STIP1 rs2236647 and GLCCI1 rs37969 in childhood asthma patients and more studies are required to repeat our findings." (PMID 33208131, 2020). "However, according to the currently reported GWAS, the STIP1 gene has not been found to be associated with asthma sensitivity, whether in African American, Asian, Caucasian or Latino." (PMID 33208131, 2020).
Ataxia (1 paper, 2024). Ataxia refers to impaired coordination of voluntary muscle movement. "Autosomal dominant spinocerebellar ataxia type 48 (SCA48) is a newly identified subtype of SCA, marked by early-onset ataxia and cognitive impairment, and is associated with mutations in the STIP1 homology and U-box-containing protein 1 (STUB1) gene." (PMID 39707479, 2024).
autism spectrum disorder (1 paper, 2015). A spectrum of developmental disorders that includes autism, and Asperger syndrome. "Some mothers of children with autism spectrum disorders (ASD) present antibodies against certain brain proteins, including antibodies against STIP1." (PMID 26398952, 2015).
biliary atresia (1 paper, 2023). A rare, biliary tract disease characterized by progressive obliterative cholangiopathy of the intra- and extrahepatic bile ducts, occurring in the embryonic/ perinatal period, leading to severe and persistent neonatal jaundice and acholic stool. "Other genes including FOXA2, GPC1, ADD3, PKD1L, EFEMP1/3, STIP1 were found to be associated with biliary atresia." (PMID 37324459, 2023). "Other studies have demonstrated that mutations in FOXA2, GPC1, ADD3, PKD1L1, EFEMP1/3, STIP1, XPNPEP1, REV1 and JAG1 genes can increase an individual’s genetic susceptibility to biliary atresia." (PMID 37324459, 2023).